KRAS (KRas proto-oncogene, GTPase)
Diseases named in the same sentence as KRAS in open-access papers (continued):
Sharing a sentence is not in itself a finding about the gene and the disease.
pancreatic cancer (continued). "Furthermore, three reports showed that in KRAS-driven cancers such as pancreatic cancer, RAF/MEK/ERK kinase cascade and the autophagy pathways cooperate to maintain tumor survival and, as such, the combined inhibition of both pathways was highly efficacious at inhibiting tumor growth." (PMID 38051103, 2023). "While some reports suggest that disrupting the PHB-CRAF interaction could impair oncogenic RAS-driven pancreatic cancer through the ERK-MAPK signaling pathway, it is widely believed that merely deleting CRAF produces minimal effects in KRAS-mutated pancreatic ductal adenocarcinomas (PDAC)." (PMID 38111008, 2023). "However, pancreatic tumor cells driven by oncogenic KRAS exhibit constitutive NF‐κB activation, suggesting that additional conditions or factors are required for NF‐κB activation in the context of oncogenic KRAS." (PMID 37964407, 2023). "Importantly, KRB-456 inhibits P-MEK, P-AKT, and P-S6 levels in vivo and inhibits the growth of subcutaneous and orthotopic xenografts derived from patients with pancreatic cancer whose tumors harbor KRAS G12D and KRAS G12V and who relapsed after chemotherapy and radiotherapy." (PMID 38051103, 2023). "Thus, this regulatory mechanism disrupted by oncogenic KRAS may represent a novel vulnerability in KRAS-dependent cancers such as pancreatic cancer and others." (PMID 37686149, 2023). "Moreover, recent studies indicated that hsa‐miR‐223‐3p as an onco‐miRNA could suppress SLC4A4/KRAS signaling pathways and lead to cancer malignancy in kidney and pancreatic cancers." (PMID 36468451, 2023). "Pan-KRAS inhibitors, such as the one described here, merit clinical testing in patients as they stand to affect the clinical outcomes of patients with KRAS-driven cancers, including those with lung, colorectal and pancreatic cancer as well as further less-frequent cancer types." (PMID 37258666, 2023). "None of the tumors in the patients with pancreatic cancer was identified to harbor KRAS mutations." (PMID 35962206, 2022). "Some pancreatic cancers have activating mutations in BRAF but not in KRAS." (PMID 36556296, 2022). "Although the intriguing connection between KRAS genotype and FcRn expression level remains blurred, the two critical regulators of albumin metabolism have demonstrated synergistic impacts on the sensitivity of pancreatic cancer to albumin-conjugated drugs both in vitro and in vivo." (PMID 35154489, 2022). "Thus, our data demonstrated that gossypol may trigger apoptotic cell death in pancreatic cancer cells exhibiting wild-type and mutant KRAS with low toxicity to normal cells." (PMID 35283426, 2022). "Non-transformed human pancreatic nestin expressing (HPNE) and mutant KRAS G12D-transformed HPNE (HPNE-KRAS) cells were used in this study to evaluate the impact of alcohol in a defined cellular and genetic context relevant to the most common early mutation event in pancreatic cancer." (PMID 35454872, 2022). "Thus, KRAS is considered an effective target for pancreatic cancer therapy." (PMID 36358856, 2022). "LINC01420 could enhance MYC binding with KRAS promoter in the nucleus of pancreatic cancer cells." (PMID 35139853, 2022). "Preclinical studies on various pancreatic cancer mouse models demonstrated that KRAS G12D siRNA could be effectively transferred to the tumor site, induce prominent regression in tumor size, and prolong survival, holding remarkable potential for PDAC treatment." (PMID 35014625, 2022). "Therefore, we first investigated whether the mutagenic KRAS affects the alt-EJ repair pathway in pancreatic cancer cell lines." (PMID 36077614, 2022).
pancreatic cancer (continued). "In addition, SEMA3C inhibition sensitized KRAS or MEK1/2 inhibition in pancreatic cancer cells." (PMID 35785187, 2022). "It is the first report to focus on the possibility that MYEOV may act as a competing endogenous RNA (ceRNA) to form an interactive network with some pancreatic cancer-related genes such as KRAS and serve as a key therapeutic target of pancreatic cancer treatment." (PMID 36358856, 2022). "However, exosomes have therapeutic potential to control KRAS-dependent pancreatic cancer." (PMID 35409064, 2022). "The KRAS selectivity of the drug conjugate using dextran with the right size was then assessed, and any favorable in vivo effects, in particular, relief of the tumor immune microenvironment, were studied using multiple complementary pancreatic tumor mouse models." (PMID 35154474, 2022). "Obesity is a notable modifiable risk factor for pancreatic cancer and studies have shown that by serving as a second hit, obesogenic HFD drastically promoted oncogenic KRAS-mediated PDAC development, suggesting that pancreatic acinar cells harboring oncogenic KRAS are vulnerable to HFD challenge." (PMID 35681705, 2022). "Furthermore, regulation of KRAS occurs by phosphorylation of tyrosine residues by members of the Src family of tyrosine kinases (SFKs), three of which, Src, Fyn, and Yes, are expressed in pancreatic cancer cell lines." (PMID 36048281, 2022). "In our study, we found that either trametinib or JQ1 alone could inhibit the proliferation of some pancreatic cancer cell lines with KRAS alterations, irrespective of the mutational loci of KRAS and the mutational status of the other driver genes." (PMID 35468095, 2022). "Ewing sarcoma protein (EWS) gene rearrangements and kirsten rat sarcoma viral oncogene homolog (KRAS) gene mutation status are detected and quantified using EVs isolated by Click Beads and matched with those identified in biopsy specimens from Ewing sarcoma or pancreatic cancer patients." (PMID 35486030, 2022). "Examination of 9a’s efficacy in a panel of pancreatic cancer cell lines with varied mutational status and reliance on KRAS suggests compound binding to other G4 structures, as there was no identified correlation with KRAS dependency and compound 9a’s activity." (PMID 36011352, 2022). "Therefore, KRAS silencing-based siRNA might provide a promising option for the treatment of pancreatic cancer." (PMID 34575504, 2021). "Moreover, inactivation of Icmt enhanced KRAS-induced pancreatic cancer in mice, suggesting that inhibition of ICMT activity may be counterproductive in some cancers." (PMID 34947990, 2021). "The goal of this study was to determine whether pancreatic cancer cells retain their viability and tumorigenic capacity independent of KRAS, to identify stages of tumor progression when KRAS is essential, and to explore changes that enable cancer cells to escape from KRAS dependence." (PMID 33674596, 2021). "Given the fact that KRAS alterations are a hallmark driver mutation and occur in the vast majority of pancreatic cancers, whether or not the absence of KRAS mutations played a role in immune surveillance in our patients requires further investigation." (PMID 34375311, 2021). "In summary, the tetracycline-controlled expression models for pancreatic cancer have been instrumental for the identification of cellular processes and molecular pathways by which a subset of cancer cells can escape a targeted ablation of KRAS and its downstream effector c-MYC." (PMID 34491463, 2021). "Similarly, the G4 ligand nitidine, or TINA-modified oligonucleotides (insertion of (R)-1-O-(4-(1-pyrenylethynyl)phenylmethyl]glycerol to increase stability) that mimic G4 structures of KRAS down-regulate KRAS protein expression and inhibit pancreatic cancer cell growth." (PMID 33632214, 2021).
pancreatic cancer (continued). "These KRAS alterations have been identified in 25% of all cancers, such as blood, breast, colorectal, gynecological, lung, prostate, and pancreatic cancer, in which some cancers, pancreatic cancer (90%), colorectal cancer (52%), and lung adenocarcinoma (32%) have extremely high mutation rates." (PMID 34744708, 2021). "KRAS has been regarded as an important predictor of pancreatic cancer progression and understanding its role may provide valuable information that might help in the development of effective pancreatic cancer therapies." (PMID 33643376, 2021). "Consequently, NBF-006 entered a phase 1 trial that investigated the GSTP knockdown impact on patients with NSCLC, colorectal or pancreatic cancer with or without KRAS mutation." (PMID 34371702, 2021). "Furthermore, the transcription factor ONECUT2 was identified as a putative driver of early progression of pancreatic cancer whose role in the activation of the KRAS pathway was sufficient to induce acinar hyperplasia, although the neoplastic lesions developed focally." (PMID 34745998, 2021). "However, there was no comprehensive analysis to explore KRAS-associated metabolic signature or risk model for pancreatic cancer (PC)." (PMID 34660806, 2021). "Therefore, it is speculated that pancreatic cancer cells lose p16 activity in order to gain the survival advantage offered by mutant KRAS." (PMID 38107772, 2021). "Hence, development of KRAS targeting in pancreatic cancer therapeutics remains of essence." (PMID 34781949, 2021). "It has been reported that oncogene ablation-resistant pancreatic cancer cells depend on mitochondrial function and that resistance to KRAS-targeted therapy might be mediated by a subset of tumor cells that depend on oxidative phosphorylation for survival instead of the classic Warburg effect." (PMID 34916936, 2021). "Therefore, the combination of verteporfin and pan-RAF inhibitors may be a potential approach for treating KRAS-mutant pancreatic cancer." (PMID 33408779, 2021). "Interestingly, AMD3100 reduced the proliferation of Hs766t, a CXCL12+ KRAS wild-type (WT) pancreatic tumor cell line, suggesting an autocrine regulatory loop that may be at play in some pancreatic tumors." (PMID 35008248, 2021). "Collectively, this study revealed that environmental damage, in combination with KRAS mutation, induces BRD4-dependent epigenetic reprogramming, as well as identified IL-33 as an effector of environmental damage to drive early-stage neoplasia for pancreatic cancer initiation." (PMID 34023857, 2021). "In addition, a recent study reported that ubiquitination signaling could activate KRAS and promote macropinocytosis in pancreatic cancer." (PMID 34073722, 2021). "Therefore, simultaneous targeting of multiple pathway components may prove beneficial in the treatment of KRAS-mutant pancreatic tumours, if toxicities remain manageable." (PMID 33546207, 2021). "The KRASG12R mutational isoform is uniquely more prevalent in pancreas cancer compared to other KRAS-driven solid organ cancers and was previously shown to be a negative prognostic factor for overall survival compared to pancreatic cancers with KRAS G12D or G12V mutations." (PMID 33405090, 2021).
pancreatic cancer (continued). "In addition to direct metabolite supply, activated PSCs can be particularly stimulated by oncogenic KRAS in adjacent pancreatic cancer cells, reciprocally enhancing downstream pathways of oncogenic KRAS signaling in cancer cells, including metabolic regulation." (PMID 32122374, 2020). "Functional study of pancreatic cancer has shown that stimulation of ER stress under the mutant KRAS expressing condition, which has higher sensitivity to stimulants for ER stress, such as tunicamycin, brefeldin A, and bortezomib, results in an anticancer effect in mutant KRAS expressing conditions." (PMID 32728173, 2020). "In order to analyze the time course effect of gemcitabine treatment on VMP1 expression we used PANC-1 and MIAPaCa-2 pancreatic tumor cells harboring a KRAS activating mutation, that are highly resistant to chemotherapy, and BxPC-3 pancreatic tumor cells that do not carry KRAS mutation." (PMID 32655498, 2020). "Significant efforts have been made to identify new pancreatic cancer-associated antigens, preferably shared by the majority of patients, such as carcinoembryonic antigen (CEA), mucin-1 (MUC-1) and the product of mutated KRAS, to develop targeted vaccination strategies." (PMID 35582441, 2020). "However, the association of this signature to KRAS mutation has not been evaluated, although KRAS mutation itself is a poor prognostic factor of pancreatic cancer, suggesting a possible link between the oncogenic driver status and this signature." (PMID 32725342, 2020). "Furthermore, functional testing of miR181ab1’s function in other mutant-KRAS tumors beyond lung and pancreatic cancer would be highly interesting, as those could also benefit from direct inhibition of this miRNA cluster." (PMID 31874105, 2020). "Therefore, KRAS is usually selected as the target gene in screening for pancreatic cancer ctDNA." (PMID 32707720, 2020). "Besides, a mutation in KRAS alone is not sufficient to provide genetic evidence of pancreatic cancer." (PMID 32704002, 2020). "Kirsten rat sarcoma 2 viral oncogene homolog (KRAS) makes a critical contribution to the initiation and progression of pancreatic cancer via affecting diverse cellular events and G12D is one of notable missense mutations, constitutively activating KRAS in cancer cells." (PMID 32756339, 2020). "Although tissue-specific differences may account for some of these discrepancies in miR181ab1 expression and function, the data described here unequivocally demonstrate that miR181ab1 functions as a pro-oncogenic miRNA in lung and pancreatic tumors in which the KRAS oncogene is expressed." (PMID 31874105, 2020). "g., a study on KRAS targeting may be attributed to pancreatic cancer research)." (PMID 33014285, 2020). "PAI-1 could be upregulated by KRAS in pancreatic cancer cells through ERK." (PMID 31695760, 2019). "The combined/synergistic effect of genetic mutation of KRAS in the pancreas and obesity, a life-style factor on suppression of natural killer (NK) cells at the pre-neoplastic stage of pancreatic cancer has not been investigated and is the subject of this report." (PMID 29977235, 2018).
pancreatic cancer (continued). "Interestingly, a recent study showed that mutated KRAS can induce abnormal regulations of pancreatic transcription factors including HNF-1B, which in turn causes abnormal cell growth and proliferation that leads to pancreatic cancer." (PMID 30065837, 2018). "Thus, our data suggest that matrine might be an effective candidate as a therapeutic agent for KRAS‐mutant pancreatic cancer." (PMID 29791786, 2018). "However, KAN0439834 was equally effective in inducing apoptosis of pancreatic cancer cell lines irrespective of KRAS mutation." (PMID 29856777, 2018). "Notably, this analysis suggests that 75% of pancreatic cancer cases are KRAS mutated rather than the widely quoted >90%." (PMID 30287508, 2018). "However, whether an interaction involving miR-217, MALAT1 and KRAS occurs in pancreatic cancer remains unknown." (PMID 28701723, 2017). "While KRAS mutations themselves have been associated as prognostic markers, there is considerable and significant heterogeneity in the activation states of the downstream MAPK/ERK pathway, the molecular landscape, response to therapy, and clinical outcome across pancreatic cancers." (PMID 28732488, 2017). "In conclusion, at a detection limit of 0.08% allelic fraction, our amplicon-based KRAS mutations sequencing assay applied to a large case-control series of plasma samples showed a limited sensitivity of 21.1% for the detection of pancreatic cancer and was not as specific as anticipated." (PMID 27705932, 2016). "Our findings indicate that recombinant PTD-RBD-VIF, a chimeric protein with a combined cellular-viral origin, could be further developed for the treatment of various tumors harboring mutant or over-activated KRAS, especially for cases presenting with pancreatic cancer recurrence after surgery." (PMID 27322423, 2016). "Also, miR-3923 might act as an inhibitor in the tumorigenesis of pancreatic cancer by mediating the regulation of lncRNA-NUTF2P3-001 on KRAS expression." (PMID 26755660, 2016). "Those non-hotspot cfDNA KRAS mutations identified in pancreatic cancer cases may reflect the heterogeneity of the tumors or the alterations of genetically different metastatic lesions." (PMID 27705932, 2016). "Modulation of KRAS activity by upstream signals has revealed a promising new approach for pancreatic cancer therapy; however, it is not clear whether microRNA-associated KRAS axis is involved in the carcinogenesis of pancreatic cancer." (PMID 25905463, 2015). "The balance between glutamate dehydrogenaseand aminotransferase activity in tumor cells has been shown to vary as demonstratedby changing KRAS expression in pancreatic cancer cells, so the actual direction of flux between glutamate andα-ketoglutarate may vary depending on cell type." (PMID 25749035, 2015). "An approach to identify potentially targetable subpopulations of pancreatic cancers is to examine other mutations that may be able to initiate pancreatic tumorigenesis independent of KRAS." (PMID 26436951, 2015). "Since both the ERK and PI3K pathways are effectors of KRAS, activating mutations of KRAS reinforce the crosstalk between insulin/IGF-1 receptor and GPCR signaling systems, thereby increasing the robustness of the network induced by insulin/IGF-1 and GPCR agonists in pancreatic cancer cells." (PMID 25295009, 2014).